SIRT1 (sirtuin 1)
Diseases named in the same sentence as SIRT1 in open-access papers (continued):
Sharing a sentence is not in itself a finding about the gene and the disease.
cancer (continued). "Previously, our laboratory has identified a SUMOylation dependent pathway wherein the SUMO E3 ligase PIASy (PIAS4) represses SIRT1 expression in response to hypoxia in cancer cells." (PMID 27285989, 2016). "All these data indicate that CCAR2 depletion inhibits selectively the proliferation of cancer cells, in a SIRT1 independent manner, by reducing AKT activation." (PMID 27809307, 2016). "Although its role in cancer remains contradictory, recent studies showed that patients expressing high levels of SIRT1 had a higher chance of being resistant to chemotherapy than patients with low SIRT1 expression." (PMID 27226812, 2016). "Collectively, these results suggest that some SIRT1-dependent, fibroblast-derived factors stimulate cancer proliferation depending on the cell context." (PMID 26992208, 2016). "SIRT1 contributes to cancer cell death by inhibiting tumor growth; however, it also supports cancer cell growth and survival by upregulating oncogenic signaling pathways." (PMID 28070138, 2016). "When these cancer cells were incubated in the media from SIRT1-deficeint fibroblasts, the growth rate was significantly declined." (PMID 26992208, 2016). "We concluded that cancer growth is promoted by SIRT1 in stromal cells but demoted by SIRT1 in cancer cells." (PMID 26992208, 2016). "As pointed out by Roth and Chen, despite the controversy over the role of SIRT1 in tumorigenesis, it appears that SIRT1 has a consistent role in mediating cancer cell survival." (PMID 26999517, 2016). "Although the SIRT1 expression in cancer cells tends to correlate with patients' survival, two survival curves are not statistically different." (PMID 26992208, 2016). "Several reports have shown that SIRT1 expression is a prognostic indicator for many cancers including GC." (PMID 28070138, 2016). "Several reports have shown that resveratrol has inhibitory effects on various types of cancer cell lines and preclinical animal models of various cancers, such as colon, breast and lymphoma, through its activity on diverse subcellular targets, including Sirt1." (PMID 26959057, 2016). "The growth of B16F10, SKVO3, or SNU840 cells was increased in conditioned media from SIRT1-overexpressing MEF-1 or CCD18Lu cells, and the growth of SIRT1-overexpressing cancer cells was further retarded in the media." (PMID 26992208, 2016). "All together, our data support that competitive interaction of KU70 by LSD1 and SIRT1 in cancer cells in response to stress regulates NHEJ repair and mutation acquisition." (PMID 27384990, 2016). "Here, we demonstrated that SIRT1 is essential for galangin-induced autophagy, suggesting that SIRT1 and autophagy play an anti-cancer role under the treatment of galangin." (PMID 27460655, 2016). "Although SIRT1 stimulates cancer proliferation by blocking cellular senescence and disrupting cell-cycle arrest, Wang considered SIRT1 to be a tumor suppressor, given that the activation of SIRT1 by resveratrol partially inhibited tumor formation." (PMID 27081083, 2016). "The cytosolic accumulation of Sirt1 has been observed to be a special feature in various cancer cells." (PMID 27171144, 2016). "The results support our notion that SIRT1 in stromal cells promotes cancer progression, but the clinical consequence of SIRT1 expression in cancer cells remains to be further investigated." (PMID 26992208, 2016). "Briefly, fibroblast SIRT1 promotes tumor growth by enforcing cancer-stroma interplay, whereas cancer SIRT1 inhibits tumor growth." (PMID 26992208, 2016). "Because APE1 is known to be phosphorylated, it is possible that such modification of APE1 in cancer cells enhances its interaction with p300 to induce acetylation or decrease its interaction with HDAC1/SIRT1 to maintain enhanced level of APE1 acetylation." (PMID 27655688, 2016). "Both oncoprotein and tumor-suppressor activity have been reported for SIRTUIN1 (SIRT1) and p38 in many types of cancer." (PMID 26824501, 2016).
cancer (continued). "Inactivation of these tumor suppressor genes or activation of oncogenes such as E2F1, c-Myc, and STAT5 in pre-cancer and cancer cells enhance SIRT1 expression." (PMID 27708228, 2016). "In the present study, we first explored the roles of SIRT1 in tumor growth based on the concept of cancer-stroma interplay." (PMID 26992208, 2016). "Particularly, Sirt1 inhibits NF-κB, which is a promoter of inflammation, survival, and cancer metastasis." (PMID 27379175, 2016). "In our experimental settings, SIRT1 in cancer cells is characterized to play a tumor suppressive role, but the precise action of SIRT1 in cancer was not further investigated." (PMID 26992208, 2016). "Previous studies also demonstrated that SIRT1 is overexpressed in some cancers and has an obvious correlation with poor prognosis of patients by promoting tumor metastasis." (PMID 27566573, 2016). "A dual function in tumor promoting and suppression has been described for SIRT1, being upregulated in some cancer types and downregulated in others." (PMID 26701732, 2016). "SIRT1 has been attributed roles in tumor formation and is a regulator of metabolism, a process that interconnects with cancer." (PMID 27494892, 2016). "SIRT1-overexpressing cancer cells exhibited slow growth, and the growth was further inhibited in co-culture with SIRT1 knocked-down fibroblasts." (PMID 26992208, 2016). "Overexpression of SIRT1 in mice strains was shown to reduce incidence of several age-related diseases such as cardiovascular disease, metabolic disease, and cancer." (PMID 26672058, 2016). "Collectively, these findings suggest that breast epithelial cells in tissues of BRCA1-mutation carriers also exhibit misregulation of SIRT1 expression as well as DDR and pRb pathway activation before the onset of cancer." (PMID 26106036, 2015). "Intriguingly, SIRT1 overexpression specifically in brain increases longevity by approximately 11% in both male and female mice, and also reduces incidence of cancer." (PMID 25907989, 2015). "Conversely, the inhibition of SIRT1/2 was shown to be effective in inhibiting cell proliferation, while inducing apoptosis in cancer cells." (PMID 25569080, 2015). "SIRT1 plays a critical role in multiple aspects of cancer drug resistance, and promotes the survival of CSCs." (PMID 25826085, 2015). "SIRT1 expression has been reported to be higher in variety of human cancer cell lines and tissues including PCa." (PMID 26439987, 2015). "There are reports describing decreased SIRT1 expression in various cancers including ovarian and bladder malignancies." (PMID 26121130, 2015). "Sirtuin 1 (SIRT1) and sirtuin 2 (SIRT2) are NAD+-dependent protein deacetylases involved in the regulation of key cancer-associated genes." (PMID 25915617, 2015). "Due to this, factors that are upregulated in cancer cells that can regulate lipid metabolism, such as SIRT1, are attractive targets for study." (PMID 25569080, 2015). "In some cancers, SIRT1 expression is often increased in tumors as compared to benign adjacent tissue." (PMID 25569080, 2015). "For example, aberrant DNA methylation of SIRT1 is frequently observed in different cancers and played an important role in carcinogenesis." (PMID 25774687, 2015). "All these evidence suggests an important role of SIRT1 in determining the antioxidant capacity of cancer cells and hence the outcome of chemotherapy." (PMID 26008972, 2015). "SIRT1 is important in a huge diversity of cellular processes such as DNA repair, apoptosis, cell proliferation, metabolism, and cancer." (PMID 26468954, 2015).
cancer (continued). "Early studies demonstrated that SIRT1 is involved in epigenetic silencing of genes whose promoters are hypermethylated in cancer cells." (PMID 26622943, 2015). "SIRT1 has also been observed to promote tumor growth and overall survival and progression of cancer cells." (PMID 26694419, 2015). "SIRT1 overexpression has been noted in several cancers, including prostate, AML and colorectal cancer, whilst SIRT3 and SIRT7 levels have been demonstrated to be overexpressed in node-positive breast cancer." (PMID 26121130, 2015). "SIRT1 was originally identified as a nuclear protein, however some studies have found the protein in the cytoplasm of cancer cells." (PMID 25915617, 2015). "Since their discovery, Sirt1 activators have been investigated in various animal models and diseases including cancer, cardiovascular diseases and neurodegeneration, involving various drug forms and dosages." (PMID 24416337, 2014). "In certain tumor tissues, the cancer cells were stained in a scattered pattern, and the ratio of the Sirt1-positive cells in such tissue was <10%." (PMID 24959282, 2014). "In all cancer and normal tissues, the expression of SIRT1, N1IC, and Snail were presented mainly in high expression status." (PMID 25420528, 2014). "Our results showed that SIRT1 inhibits the EMT process in cancer by deacetylating Smad4 and repressing the effect of TGF-β signaling on MMP7." (PMID 25424420, 2014). "While the SIRT2 and SIRT6 actually appear to be tumor suppressors, the most frequently studied subform SIRT1 seems to conditionally operate either as a tumor suppressor or as cancer promoting factor." (PMID 25310649, 2014). "Our data builds upon the results in these previous studies by further verifying SIRT1 as a critical regulator of cancer progression, and an important target for prevention or possible treatment of cancer metastasis." (PMID 25424420, 2014). "SIRT1 is a pleiotropic protein that plays critical and multifunctional roles in metabolism, senescence, longevity, stress-responses, and cancer, and has become an important therapeutic target across a range of diseases." (PMID 24566137, 2014). "An increased expression of SIRT1 has been reported in a variety of human cancers, including prostate, ovarian, gastric and colorectal cancer." (PMID 24603648, 2014). "SIRT1 and AMPK are two energy metabolic sensors, and metabolism alteration is a crucial hallmark of cancer." (PMID 24742694, 2014). "SIRT1 has been shown to be upregulated in several cancers such as prostate cancer, cutaneous T-cell lymphoma, colorectal cancer and pancreatic cancer." (PMID 24743044, 2014). "Nonetheless, it is worthy of note that such conflicting functions of SIRT1 were determined by studies of SIRT1 expression in cancer and its effects on well-known oncogenes and tumor suppressors." (PMID 25146318, 2014). "Cancer cells tend to require these functions of SIRT1 in order to survive, proliferate, and repair catastrophic genomic damage." (PMID 25033286, 2014). "JQ-101 suppressed cancer cell growth and survival by targeting SIRT1, and also exhibited selective cytotoxicity towards a panel of human tumor cell lines, while producing no toxicity in two normal human cell types at comparable concentrations." (PMID 25189993, 2014). "The class III HDAC family member SIRT1 has been shown to protect against cardiovascular diseases, cancer, and neurodysfunction." (PMID 24466304, 2014).
cancer (continued). "SIRT1 has originally been described as a target of resveratrol although some of the data are still controversial, especially concerning resveratrol acting as SIRT1 activator in cancer cells." (PMID 24603648, 2014). "To further study the specificity of JQ-101 mediated cancer cell growth, we treated the both SIRT1-silenced and vector control-transfected H460 cancer cell lines with JQ-101." (PMID 25189993, 2014). "Here we report the identification of a new SIRT1 inhibitor, JQ-101, which induces cancer cell apoptosis and senescence, suppresses cancer cell invasion, and exerts cancer-specific cytotoxity, repressing tumor cell growth." (PMID 25189993, 2014). "Although much research has been performed on SIRT1, its role in tumorigenesis in specific cancers, even in the same cancer type, is still controversial." (PMID 25922660, 2014). "During aging, SIRT1 expression and its activity declined while it is highly expressed in several types of cancer cells." (PMID 25247581, 2014). "Current studies in animal models are examining the biological functions of SIRT1 activators with the aim of identifying cancer treatments." (PMID 25486244, 2014). "SIRT1 is up-regulated in malignant cells in a variety of cancers, and has a particularly important role in cancer drug resistance." (PMID 24967705, 2014). "Consistent with our findings, it has been shown that SIRT1 inhibition reduces cancer cell migration and invasion while SIRT1 activation promotes cancer metastasis." (PMID 25189993, 2014). "One study revealed that SIRT1 regulates critical biological processes, including metabolism, aging, DNA damage, apoptosis, and cancer progression." (PMID 25522783, 2014). "JQ-101 will also serve as a novel chemical scaffold for future development of more potent SIRT1 inhibitors to be used in cancer treatment." (PMID 25189993, 2014). "Sirtinol, a specific inhibitor of Sirt1, has been shown to induce apoptosis of cancer cells by elevating endogenous level of reactive oxygen species." (PMID 25184156, 2014). "The protein deacetylase SIRT1 is involved in the regulation of a large number of cellular processes that are thought to be required for cancer initiation and progression." (PMID 25380034, 2014). "These highly variable observations suggest that the molecular, physiological and environmental contexts are critical in defining the role of SIRT1 in cancer." (PMID 25380034, 2014). "In vivo studies show that SIRT1 inhibition suppresses tumor growth, metastasis and progression in several cancer types, including prostate, breast and neuroblastoma." (PMID 25189993, 2014). "The results from our study agree with published research in that FZD7 has an important role in cancer cell growth and development, and we have shown that SIRT1 can regulate the expression of this critical receptor at the transcriptional level." (PMID 24897117, 2014). "Previous studies showed that Sirt1 overexpression in cancer correlates with silencing of tumor suppressor genes." (PMID 25184156, 2014). "Certain study results indicate that regulated transcription of Sirt1 levels in cancer cells can affect the expression level of Sirt1." (PMID 24959282, 2014). "A better understanding of the role of SIRT1 in specific tissues will provide the molecular basis for development of novel anti-aging and anti-cancer therapeutic targets." (PMID 24742694, 2014).
cancer (continued). "A recent study identified a positive feedback loop consisting of MYC, the nicotinamide-phosphoribosyltransferase (NAMPT) enzyme, the SIRT1 inhibitor deleted in breast cancer 1 (DBC1) and SIRT1." (PMID 24884974, 2014). "The correlation between SIRT1 expression and tumor metastasis in several types of cancer has aroused widespread concern." (PMID 25522783, 2014). "If we simply assume that SIRT1 is a tumor promoter, whereas DBC1 a tumor suppressor counteracting SIRT1, the relative abundance of SIRT1 to that of DBC1 should be elevated in cancers." (PMID 25146318, 2014). "Our work described Sirt1's expression related to that of Ccar2 (Cell cycle and apoptosis regulator 2, also named Deleted in breast cancer 1 or KIAA1967), a protein that directly inhibits the deacetylation activity of Sirt1." (PMID 25594010, 2014). "In contrast, the NAD-dependent deacetylase SIRT1 is significantly higher expressed in both cancer cell lines compared to primary human hepatocytes (HepG2 cells 2.8-fold, Hep3B cells 2.5-fold)." (PMID 24603648, 2014). "Overexpression of SIRT1 was found in many cancers, such as stomach and colon, and reported to function as a tumor promoter." (PMID 25033286, 2014). "The higher expression of SIRT1 in chemoresistant types of cancer cells raises the possibility that the increased expression of SIRT1 in the poor prognostic group of cancer is the consequence of the progression of cancer." (PMID 24019980, 2013). "The apoptotic effect was ascribed to the activation of proapoptotic genes repressed in cancer cells by Sirt1." (PMID 24069483, 2013). "Concerning to the role of SIRT1 in human malignant tumors most studies demonstrated that the expression of SIRT1 in human tissue related to the survival of cells and present benefits to the survival of cells despite some controversies." (PMID 24019980, 2013). "Among these, SIRT1 expression negatively correlates with cancer survival in both laboratory and clinical studies." (PMID 24258275, 2013). "Sirt1 is an important deacetylase involved in numerous molecular events, including metabolism, cancer, embryonic development and immune tolerance." (PMID 24073240, 2013). "The data suggest that AROS, as well as SIRT1, promotes survival in cancer cells while being redundant for viability in non-cancer cells." (PMID 24258275, 2013). "Hypermethylated in cancer-1 (HIC1) is a transcriptional repressor of the SIRT1 promoter [[A48]] that helps prevent age-dependent cancers in mice." (PMID 24360018, 2013). "Considering the multitude of cellular pathways it affects, SIRT1 appears to play a rather complex role in the biology of cancer, and evidence supports both tumor promoting and tumor suppressing functions." (PMID 23799088, 2013). "With regard to SIRT1 it is known that its expression is increased in a variety of human cancers including PCa, suggesting a critical role of this protein in tumorigenesis." (PMID 23658738, 2013). "SIRT1 was initially considered to be an exclusively nuclear protein, while cytoplasmic staining of SIRT1 was recognized in a small number of cancers." (PMID 23805287, 2013). "Another explanation would be that cytoplasmic Sirt1 plays a major role in the development of carcinogenic precursors and nuclear Sirt1 has its place in the fully developed cancer." (PMID 24088390, 2013). "Among genes repressed in a SIRT1-dependent manner was a set of genes frequently inactivated by DNA methylation in human cancers, providing direct evidence that SIRT1 controls expression of tumor suppressor genes." (PMID 23799088, 2013).